EGFR (epidermal growth factor receptor)
Diseases named in the same sentence as EGFR in open-access papers (continued):
Sharing a sentence is not in itself a finding about the gene and the disease.
tumor (continued). "More recently, other studies have also reported emergence of KRAS mutations in liver metastases after anti-EGFR treatment, highlighting the role of intra-tumour heterogeneity as a major contributing factor for intrinsic and/or acquired resistance to anti-EGFR mAbs." (PMID 33562755, 2021). "In addition, EGFR activation, as determined by immunostaining with an anti-EGFR pTyr1148 antibody, was dramatically downregulated in tumor tissues treated with cetuximab alone or in combination with dasatinib." (PMID 32989241, 2021). "Reduced oxygen supply has been shown to have an impact on EGFR and its signal cascades and has been related to insistence on anti-EGFR strategies in various tumor cell lines both grown in culture or as xenograft tumors as well as in human HNSCC tumors including our previous work." (PMID 33718186, 2021). "The TAT from tumor sampling to EGFR genotyping request was comparable whether genotyping was ordered from IdyllaTM or performed using the NGS method, with a timeframe of 5.3 ± 3.6 wd (7.4 ± 5.1 cd) and 5.6 ± 3.7 wd (7.8 ± 5.1 cd), respectively." (PMID 34898548, 2021). "Furthermore, the sequencing results showed that the EGFR gene was deleted, which was confirmed by immunohistochemistry since the tumor was EGFR-negative in immunohistochemical staining." (PMID 33313992, 2021). "Therefore, circ_CELF1/miR-491-5p/EGFR axis involved in NSCLC tumor procession, which would provide a new therapeutic target for NSCLC." (PMID 34788230, 2021). "Furthermore, we performed exploratory analyses into differing effects according to tumour sidedness and CMSs to further define anti-EGFR therapy efficacy." (PMID 34253874, 2021). "However, genotyping of tumors, including EGFR analysis, can be limited by the need for tumor tissue samples that are collected via biopsy, which is often contra-indicated in patients with advanced disease." (PMID 34574036, 2021). "The analysis was performed by pooling the efficacy of CT plus an anti-EGFR agent crossover to CT plus an anti-VEGF agent, versus CT plus an anti-VEGF agent crossover to CT plus anti-EGFR agent on the OS of patients with KRAS-WT who had different tumor localization." (PMID 34768686, 2021). "However, EMT can be a strategy by which a tumor can escape it’s dependence on EGFR activity, e.g. in NSCLC." (PMID 34162346, 2021). "In tumor tissues derived from EGFR-low cells, cetuximab treatment caused no significant changes in the numbers of proliferative cells." (PMID 32989241, 2021). "Additionally, immunohistochemical results of study in vivo further confirmed that FGFC1 suppressed erlotinib-resistant NSCLC xenograft tumor growth through decreasing p-EGFR and Ki67 expression." (PMID 35126111, 2021). "However, in the A431 xenograft tumor, we found that EGFR expression was decreased in the pimonidazole-positive area, whereas HER2 expression was increased in EGFR decreased area." (PMID 33994540, 2021). "Similarly, Quinazoline based small molecule comprising benzazepine moiety also reduced the tumor growth with IC50 ranging from 1.06–3.55 μM by targeting EGFR-T790M." (PMID 34769090, 2021). "ALK and EGFR rearrangements may co-occur in one and the same tumor specimen, and it is already known that compound EGFR mutations feature a more aggressive behavior." (PMID 33572278, 2021). "Interestingly, EGFR806-CAR T cells, recognizing not only EGFRvIII but also full-length gene amplified wildtype EGFR, retained their specificity due to specific steric accessibility of tumor-expressed EGFR." (PMID 34884607, 2021). "Tumor-derived exosomal circRNA_102481 could contribute to EGFR-TKIs resistance in NSCLC by sponging miR-30a-5p to enhance ROR1 expression." (PMID 33952725, 2021).
tumor (continued). "Moreover, TGF-β1 can activate PI3K/AKT/mTOR signaling or promote expression of EGFR and FosB to facilitate cancer cell motility, invasion and tumor metastasis." (PMID 34203341, 2021). "In addition, our ongoing experiments have demonstrated that the human EGF fusion toxins can cross‐react with murine EGFR+ tumor cells in a syngeneic mouse tumor model." (PMID 33540470, 2021). "Thirdly, we did not carry out subgroup analyses according to tumor stage, oncogenic alteration (e.g., EGFR mutation, EML4-ALK fusion, KRAS mutation), expression status of PD-1/PD-L1, etc. due to the limitations of the data." (PMID 34497760, 2021). "By identifying the response of the patient-derived tumor cells to the EGFR-TKis, our results helped to guide our patient’s treatment to include treatment options that are currently still not generally available for these patients, but which resulted in sustained clinical benefit." (PMID 34604070, 2021). "In a GBM tumor, wild-type EGFR and EGFRvIII are co-expressed; 97% of GBM cells express wild-type EGFR while 23% of GBM show a EGFRvIII mutation, which makes these two forms of EGFR the clinically most relevant." (PMID 34948346, 2021). "Furthermore, the treatment of N1mAb suppressed EGF signals, potentiated the effect of EGFR inhibitor, and decreased the tumor growth in mouse xenograft models." (PMID 34277416, 2021). "Recent data from our group suggest that GSC-derived pericytes may be in contact with EC, acting as mural cells and enhancing the tumor vasculature, in GBM with EGFR mutations." (PMID 34361013, 2021). "Understanding how specific tumor-promoting factors such as EREG are regulated under different cellular contexts and how oncogenic mutations confer alternative signal activation can help clinicians improve treatments, such as anti-EGFR therapy." (PMID 34884633, 2021). "These may arise either as new genetic alterations in the tumor after start of therapy, or through positive selection pressure of anti-EGFR therapies on an already-present group of EGFR-resistant cells present at time of treatment initiation." (PMID 34877077, 2021). "Therefore, a WT EGFR-targeted therapy must be delivered locally to the tumor to prevent any on-target, off-tumor toxicities." (PMID 34868044, 2021). "Finally, in vivo, we observed that treatment with an anti-EGFR antibody, cetuximab injected subcutaneously, reduced tumor growth, a process that was accompanied by a decreased intra-tumoral expression of uPA." (PMID 33886813, 2021). "In the current study we show that patients with CMS2/3 tumours may benefit from anti-EGFR therapy combined with either an irinotecan or oxaliplatin backbone." (PMID 34253874, 2021). "Likewise, the EGF moiety of Fcy-hEGF will transform the passive liposome into active one specific for EGFR-overexpressing tumor." (PMID 33672989, 2021). "Tumor specific uptake of panitumumab-IRDye800 provided remarkable contrast and a flexible imaging window for fluorescence-guided identification of HGGs despite modest EGFR expression." (PMID 33707521, 2021). "Exosomal miR‐210‐3p may play a crucial role in resistance to osimertinib in the tumor microenvironment of EGFR‐mutant NSCLC." (PMID 33939301, 2021). "Previous studies have found that co-mutations may activate the alternative signaling pathway or increase tumor heterogeneity, thereby affecting the efficacy of EGFR-TKIs." (PMID 34485120, 2021). "Notably, anti-EGFR therapy especially enhances the expression of PD-L1 on tumours and the infiltration of CD8+ T cells." (PMID 34663410, 2021). "Inactivation of EGFR tyrosine kinase could result in the suppression of tumor growth, metastasis and angiogenesis, and the induction of tumor cell apoptosis." (PMID 34575576, 2021). "Thus, this bidirectional relation or cross-talk between ERα and EGFR is configured, enhancing tumor progression." (PMID 33652604, 2021).
tumor (continued). "The assumption that such a tonic PLCγ-mediated signal in tumours overexpressing wt or mutant forms of the EGFR may contribute to the resistance of such tumours to ICI treatment is directly in line with recent findings from the group of Yossi Yarden." (PMID 35052732, 2021). "We suggest that IL-17A rs8193036 SNP might affect LUAD tumor progression and its clinical course in patients harboring the WT EGFR and MT KRAS." (PMID 33802737, 2021). "This study examined the feasibility of detecting human HGGs via fluorescence imaging using panitumumab-IRDye800 in a preclinical orthotopic tumor model with only modest level of EGFR expression which was benchmarked against similar expression levels in patient HGG tissues." (PMID 33707521, 2021). "However, several studies have reported high AXL expression in tumor specimens obtained after first or second EGFR-TKI treatment failure." (PMID 33572269, 2021). "Overexpression or mutation of EGFR has been observed in many human tumour cells, such as nonsmall-cell lung cancer (NSCLC), breast cancer, and brain cancer." (PMID 34074193, 2021). "Therefore, we only analyzed patients who were refractory or intolerant to standard chemotherapies [FU, OX, IRI, bevacizumab, and anti-EGFR antibody (if the patients had wild type KRAS/ NRAS tumor)] in order to minimalize the inherent bias." (PMID 33763345, 2021). "Another immunohistochemical study of 113 MGM specimens from 89 patients indicated that EGFR expression may be higher in benign MGM tumors." (PMID 34768783, 2021). "For example, we and others have demonstrated that GABARAPL1 is involved in anterograde trafficking of several receptors, including EGFR, which might influence tumour cell proliferation." (PMID 34859607, 2021). "However, the acquisition of resistance to EGFR TKIs is almost inevitable, underscoring the importance of identifying bypass signaling pathways allowing some tumor cells to survive the initial exposure to TKIs and become metastatic." (PMID 35083168, 2021). "Therefore, an increased level of EGFR, especially in tumour cells, is connected to a poor prognosis and reduced life expectancy." (PMID 34943184, 2021). "There is some evidence that patients with RAS and BRAF wildtype mesenchymal CMS4 tumours may only benefit when anti-EGFR is combined with irinotecan, even in right-sided primary tumours." (PMID 34253874, 2021). "Other similarities have been observed where CBR1 expression was positively correlated with Gleason score (rs = 0.21, p < 0.001), tumour stage (rs = 0.11, p < 0.05), percentage of the specimen that contains tumours (rs = 0.17, p = 0.01) and EGFR (rs = 0.18, p = 0.01)." (PMID 34575629, 2021). "GBMs exhibit epidermal growth factor receptor (EGFR) amplification, phosphatase and tensin homolog (PTEN) mutation, and loss of chromosome 10 all of which shift the balance toward higher ROS production within the tumor microenvironment." (PMID 34084145, 2021). "miR-1224-5p inhibits tumor progression by targeting the TNS4/EGFR axis." (PMID 34778021, 2021). "Moreover, elevated EGFR expression is detected during tumor progression from early pancreatic intraepithelial neoplasia to PDAC and has been recognized as the essential molecular alteration in pancreatic carcinogenesis." (PMID 33937024, 2021). "Here, this study analyzed the copy number variations (CNVs), mRNA and protein expression profiles, and their prognostic values of LANCL2 and EGFR in GBM specimens from TCGA database or from the tumor banks of Shenzhen Second People’s Hospital and Sun Yat-sen University Cancer Center." (PMID 34461927, 2021). "The combination of 5-FU and oxaliplatin were shown to elevate the expression of tumour-promoting proteins, such as EGFR, HER2, human epidermal growth factor receptor 3 (HER3), Akt and COX2, which rendered the cell survival and uncontrolled cell proliferation in chemo-surviving cells." (PMID 34299604, 2021).
tumor (continued). "On the contrary, the tumor burden at the time of death by suffocation was very similar among both strains, hence we suggest that an accelerated tumor growth in EGFR/MET mice could be at the origin of the accelerated death compared to EGFR mice." (PMID 34298655, 2021). "However, tumor progression inevitably occurred in the majority of NSCLC patients receiving EGFR-TKIs therapy despite the initial obvious and rapid effects of EGFR-TKIs." (PMID 33763171, 2021). "In addition, EGFR is reported to promote angiogenesis in tumors and inhibit growth and development of tumor cells." (PMID 34867408, 2021). "Our data suggest that homeobox DNA methylation could be a novel tumor cellular state that can aid the precise categorization of tumor heterogeneity in the study of IR to EGFR-TKIs." (PMID 34036228, 2021). "We then checked the downstream targets correlated with EGFR signaling for tumor progression." (PMID 33925065, 2021). "As the trispecific antibody is intended to facilitate an elevated tumor specificity due to simultaneous binding to EGFR and PD-L1 compared to the bsAb solely targeting EGFR, cell-binding experiments were performed on EGFR/PD-L1 double-positive A431 cells using flow cytometry." (PMID 34040611, 2021). "CAFs and other molecules can regulate COLs’ expression in cancer cells, such as transcription factors, mutated genes, receptors, and signaling pathways; these molecules can also affect tumor cell behavior by integrins, RTKs (e.g., EGFR), and discoidin domain receptors." (PMID 34976811, 2021). "Patients with PTEN-deficient tumours could benefit from downstream inhibition of the PI3K pathway, maybe at the level of the mammalian target of rapamycin (mTOR), with EGFR inhibitors." (PMID 33680090, 2021). "Hence, CMS4 tumours carry the worst prognosis due to a heightened metastatic propensity and an inherent resistance to chemotherapy and EGFR-blockers." (PMID 33673710, 2021). "The EGFR is a key receptor involved in signalling pathways driving tumour progression." (PMID 34936728, 2021). "The 40th day after EGFR-TKI treatment may be a reasonable time to administer radiotherapy to reach the goals of controlling tumours and reducing injury." (PMID 34631535, 2021). "EGFR could encourage tumor progression by promoting angiogenesis and cell invasion in GBM, and EGFR amplification could be a marker that played a role in prognostication, treatment, clinical trial eligibility." (PMID 34482818, 2021). "ScRNA-seq has also revealed heterogeneous tumor and immune cell populations in the TME of early-stage lung adenocarcinomas harboring EGFR mutations, among which myeloid cells, T cells, tumor-associated macrophages (TAMs), and dendritic cells (DCs) are prominent." (PMID 34745998, 2021). "Moreover, functional analysis involving the inhibition of EGFR, by using siRNA approach or its chemical blockage, reinforced the association between EGF pathway and γ2 chain in tumor progression." (PMID 33920762, 2021). "We also set out to scrutinize whether generated cattle-derived chimeric ultralong common light chain bsAbs could trigger efficient NK cell redirection, resulting in killing of EGFR-overexpressing tumor cells." (PMID 35087526, 2021). "On the contrary, increased expression of CD200R in both tumor and stroma was associated with male sex, ever-smoking status, non-adenocarcinoma histology, and advanced disease stage, while low CD200R expression was associated with EGFR mutations." (PMID 33804482, 2021). "Moreover, anti-PD-1 therapy enhanced effector T-cell function and suppressed tumor proliferation in EGFR-driven LUAD." (PMID 34088360, 2021). "The molecular status of EGFR in tumor tissue was available in 60% (15/25) of patients." (PMID 34441254, 2021).
tumor (continued). "In the AURA3 phase III trial (NCT02151981), osimertinib showed a statistically significant and clinically meaningful improvement in PFS over platinum-based doublet chemotherapy in advanced NSCLC patients whose tumours had progressed on prior EGFR-TKI therapy and were positive for T790M12." (PMID 33741979, 2021). "In one study, dendrimers conjugated with epidermal growth factor (EGF), human serum albumin (HSA) and nimotuzumab antibody (h-R3) were used to deliver siRNA against polo-like kinase-1 (PLK1) to the EGFR-overexpressing hepatocellular carcinoma cell line (HepG2) and tumor-bearing BALB/c nude mice." (PMID 33805602, 2021). "Finally, clinical trials for HER2-targeting agents in patients with HER2-amplified CRC revealed tumor shrinkage in anti-EGFR antibody-resistant tumors." (PMID 33801379, 2021). "EGFR-CAR-NK cells induce potent cell lysis and increase IFN-γ production when co-cultured with GBM cells, and intracranial NK-EGFR-CAR cell injection can effectively inhibit tumor growth and significantly extend the life expectancy of orthotopic GBM animal models." (PMID 34248623, 2021). "In this regard, GPR30 activation could imply an alternative and independent pathway to canonical ERs by contributing to the biological effects of E2 and EGFR on tumor progression." (PMID 33652604, 2021). "The EGFR/AKT signaling pathway influences tumor cell survival in many cancers." (PMID 34627260, 2021). "Activation of Wnt signaling, observed in tumor samples through the methylation of SFRP5 gene, could cause tumor resistance to EGFR TKIs and, on account of this it was associated with poorer treatment outcomes." (PMID 34885084, 2021). "Another characteristic of CMS2 tumours is a favourable response to treatment with EGFR inhibitors." (PMID 33879799, 2021). "Moreover, escape mutants of tumours that become resistant to EGFR inhibitor treatments were often mutants that overexpressed receptor tyrosine kinase, which mainly mediate tonic signals via the PLC signalling pathway, such as IGFR or cMET." (PMID 35052732, 2021). "A tumor is classified as epidermal growth factor receptor (EGFR)-positive at any immunohistochemical staining of the tumor cell membrane above the background level (Dako EGFR pharmDxTM)." (PMID 34768978, 2021). "We hypothesize that this tumor cell-intrinsic property may contribute to the heterogeneity of EGFR/ERBB inhibitor responses observed in HNSCC patients." (PMID 33485341, 2021). "In addition, the downregulation of miR-155-5p enhanced the anti- tumor effect of cetuximab in EGFR-overexpressed TNBC cells via inducing apoptosis and pyroptosis." (PMID 33472170, 2021). "EGFR is commonly overexpressed during tumor vascularization." (PMID 34830787, 2021). "For these reasons, in this review we aim to describe the role of Annexin A1 in the establishment of the tumor microenvironment, focusing on the immunosuppressive and immunomodulatory activities of Annexin A1 and on its interaction with the epidermal growth factor receptor." (PMID 34571894, 2021). "However, given that the tumor cells show apoptosis after incubation with 213Bi-anti-EGFR-MAb, it is more likely that disturbance in other processes not related to metabolism lead to lethal cell damage." (PMID 33737524, 2021). "In addition to Wnt activation, CRIS-C tumours exhibit elevated EGFR/ERBB signalling and MYC copy number gains, but typically retain wild-type KRAS, which predicts a good response to EGFR-targeted therapies." (PMID 33673710, 2021). "This EGFR gene knockdown effect could lead to tumor cell apoptosis, DNA fragmentation, and reduced microvessel blood vessel formation, especially with the LCP siEGFR NPs+PDT combined therapy." (PMID 34575510, 2021).